CD38 (CD38 molecule)
Diseases named in the same sentence as CD38 in open-access papers (continued):
Sharing a sentence is not in itself a finding about the gene and the disease.
influenza (continued). "Moreover, immune stability positively correlated to an increase in CXCR5+ CD38+ CD4+ T cells 7 days after influenza vaccination, negatively correlated to age, and was immunotype‐dependent." (PMID 36081314, 2022). "Furthermore, the frequency of activated (CD38+HLA-DR+) CD8+ T cells in severe influenza patients increased with the disease progression." (PMID 36064355, 2022). "Taken together, the ICOS+CD38++ influenza-specific CD4 T cell population that shapes the “early” activation response after seasonal influenza vaccination is characterized by high metabolic demands and phenotypic and transcriptional markers of Tfh differentiation." (PMID 34795301, 2021). "Extensive surface phenotyping was performed together with combinatorial tetramer staining to measure the frequency, memory status (CD45RA and CCR7), chemokine receptor expression (CXCR3, CCR4, CCR6 and CXCR5) as well as activation status (CD38) of these influenza-specific T cells." (PMID 27571776, 2016). "Nevertheless, despite the lower quantity of total activated CD8 T cells in dengue, influenza, adenovirus patients as well as in 3 subjects with fever of unidentified etiology, the CD38/HLA-DR expression profile on HCMV or EBV specific CD8 T cells was similar to that in acute HBV infection." (PMID 20808900, 2010). "Thus, this increased CD38 expression during pregnancy might explain the enhanced responses of NK cells to influenza and tumor cells." (PMID 31708922, 2019). "Analyzing CD8+ PBMC populations for prevalence of the CD38+HLA-DR+PD-1+ phenotype along with determining the profiles of IAV-peptide induced IFNγ production might be informative in understanding the outcome of severe influenza disease." (PMID 29483513, 2018). "CD40 L and IFNγ levels were detected after stimulating Tfh cells with an influenza antigen; the positive rates of CD27 and CD38 in B cells were detected before and after coculture with Tfh cells." (PMID 35494526, 2022). "We analyzed activated (CD38+) circulating CD4+ T follicular cells pre‐ and post‐vaccination which were previously shown to be a good predictor of influenza vaccination response." (PMID 36081314, 2022). "The peak of CD38 and HLA-DR expression corresponded to expected culmination of adaptive immune response during acute HBV, dengue and influenza infection." (PMID 35392095, 2022). "Activated HLA-DR+CD38+ CD8+ T cells were enriched over a prolonged period from the lymphopenia patients who died from Ebola and influenza infection and in severe patients infected with SARS-CoV-2." (PMID 34567001, 2021). "This concept has been confirmed in studies of seasonal influenza vaccine where cTfh have been shown to be reactivated following vaccination with memory populations cycling between ICOS+ CD38+ (activated) and ICOS− CD38− (resting) states." (PMID 36845571, 2021). "We have found that the expression of PD-1 in combination with that of the activation markers CD38 and HLADR in pTfh is inhibitory for their function in healthy volunteers given influenza vaccine." (PMID 32342859, 2020). "To gain insight into how vaccines qualitatively alter Tfh cell responses, we performed RNA sequencing of 200 ICOS+CD38+CXCR5+PD-1+ cTfh cells immediately before and 7 d after influenza vaccination in four individuals." (PMID 31175140, 2019). "In fact, a previous study using tetramer staining and activation-induced marker (AIM) assay demonstrated an expansion of the Ag.pTfh population post influenza vaccination, with co-expression of ICOS and CD38 and IL-21 production in young HCs." (PMID 31100059, 2019). "As established in our UK influenza vaccination study, we performed total RNA-sequencing on 150–200 ICOS+CD38+ cTfh cells per person before vaccination (day 0), and 7 (day 63) and 28 (day 84) d after the third vaccination." (PMID 31175140, 2019).
influenza (continued). "Similar to surviving H7N9 patients, patients hospitalized with seasonal influenza (A/H1N1, A/H3N2, and B strains) had high CD38+PD-1+ expression early after infection, followed by a decrease with recovery (p = 0.04, standard two-tail Student’s t-test)." (PMID 29483513, 2018). "An increase in frequency of CD154+CD69+CD45RO+CD38+ islet beta cell antigen specific CD4+ T cells was observed in subjects #1 and #2 14 days after influenza vaccination." (PMID 30619245, 2018). "Among these predictive subsets, several CD38+ B-cell populations (ID91, ID96, ID103, ID108) were very highly correlated with a strong antibody response to influenza vaccination." (PMID 28693586, 2017). "The peak percentage of CD8 T cells expressing CD38 and HLADR activation markers was higher in severe influenza (30%, (4–89%), p = 0.019), but varied widely in terms of timing and magnitude." (PMID 22363665, 2012). "Furthermore, previous reports showed that MAIT cells rapidly acquire the expression of exhaustion markers such as CD38, CD69, PD-1, and TIM in patients with acute viral infection by dengue or influenza." (PMID 34659215, 2021). "Similarly, highly activated CD38+HLA-DR+ CD8+ T cells, numerically greatly exceeding influenza-specific CD8+ T cell pools, were found in patients hospitalized with severe H7N9 disease, suggesting bystander activation of at least some CD38+HLA-DR+ CD8+ T cells." (PMID 31312199, 2019). "Using this approach with samples from 4 DR0401 healthy subjects, we then evaluated whether beta cell antigen specific CD38+ CD45RO+ T cells increased between the pre-vaccinated and 14 day post-influenza vaccinated samples." (PMID 30619245, 2018). "Interestingly, the HIV and ssDNA exposed CD38 + HLA DR + T cells showed higher expression of PD1, and this T cell phenotype have previously been reported in chronic HIV infection and other severe conditions such as H7N9 influenza infection." (PMID 41529066, 2026). "cTfh cells share phenotypic and functional properties to GC Tfh cells, and it has been shown that inactivated influenza vaccination (IIV) induces expansion and PD-1/ICOS-activation of CD4+CXCR5+CXCR3+ cTfh type-1 (cTfh1) cells, which correlated with antibody and CD19+CD27++CD38++ ASC responses." (PMID 33976217, 2021). "It was not possible to obtain sufficient blood to determine the frequency of influenza specific cells by ex-vivo restimulation of purified mononuclear cells so we could not verify whether HLA-DR+ CD38+ are influenza specific." (PMID 22363665, 2012). "We first tested expression of these cell-surface receptors after seasonal influenza vaccination, a routine nonadjuvanted inoculation in which cTfh cell expansion has been well described and in which expression of ICOS and CD38 has been reported on cTfh cells." (PMID 31175140, 2019).
HIV-1 infection (41 papers, 2005 to 2025). The type species of lentivirus and the etiologic agent of acquired immunodeficiency syndrome (AIDS). "HIV-1 infection characteristically induces T-cell activation markers, particularly upregulated expression of CD38 and HLA-DR, and loss of CD28 on circulating CD8 T cells." (PMID 39221258, 2024). "Here, we further delineated the susceptibility of defined HSPC subsets (CD34+CD38+ progenitors, MPPs, and HSCs) to X4 HIV-1 infection." (PMID 36230931, 2022). "HIV-1 infection causes generalized T cell activation, which is reflected in the increased CD38 expression." (PMID 32269232, 2020). "In parallel, calcitriol increased cells expressing exclusively CD38 that exhibit lower susceptibility to HIV-1 infection, reduced proliferation and increased production of IL-2 and IFN-γ." (PMID 31550271, 2019). "Given the importance of immune activation in the susceptibility to HIV-1 infection, we determined the effect of calcitriol on expression of HLA-DR and CD38 activation markers in polyclonally-activated T cells from the Co-HC." (PMID 31550271, 2019). "There was also a decrease in the MFI of CD38 expression; elevated expression of CD38 has been closely linked to poor prognosis in HIV-1 infection." (PMID 27819062, 2016). "However, impaired lineage development has also been linked to the depletion of CD34+CD38− progenitors mediated by plasmacytoid dendritic cells (pDCs) in chronic HIV-1 infection." (PMID 36230931, 2022). "In HIV-1 infection, T-cell activation levels determined by Ki67 expression or CD38+/HLA-DR co-expression as well as PD-1 expression have been associated with untreated disease progression." (PMID 37598360, 2023). "In HIV-1 infection, the combined expression of CD38, HLA-DR, and PD-1 has been shown to delineate T-cell pathogenesis distinguishing infected from healthy individuals." (PMID 34712231, 2021). "The results of this review suggest that CD38 is not only an indicator of elevated post-infection, but also an active player in HIV-1 infection." (PMID 33820568, 2021). "In a cross-sectional study of individuals with normal progressing HIV-1 infection, we previously demonstrated significantly higher percentage of CD38+CCR5+ lymphocytes compared to healthy controls." (PMID 34987508, 2021). "Lymphocytes can be activated within days of HIV-1 infection, where CD38 and HLA-DR molecules were upregulated on T lymphocytes." (PMID 33717085, 2021). "In chronic HIV-1 infection, systemic LPS levels are correlated with increased cellular immune activation, specifically with an increased frequency of activated CD38+/HLA-DR+ CD8 T cells." (PMID 31449552, 2019). "HIV-1 infection also induced similar level of CD38 and HLA-DR expression on CD8 T cells in both NRG-hu HSC and NRG-hu Thy/HSC mice." (PMID 29725337, 2018). "Strikingly, depletion of plasmacytoid dendritic cells (pDCs) prevented human CD34+CD38- early HPCs from HIV-1 infection-induced depletion and functional impairment and restored the gene expression profile of purified CD34+ HPCs in humanized mice." (PMID 28759657, 2017). "The depletion of CD34+CD38- early HPCs in human BM from HIV-1 infection was strengthened by the addition of more patients (n = 5)." (PMID 28759657, 2017). "In this study, we found that CD34+CD38- early HPCs were preferentially depleted during chronic HIV-1 infection, which correlated with the depression of hematopoiesis development and dysregulated gene expression in bulk Lin-CD34+ HPCs." (PMID 28759657, 2017). "The present study demonstrates, for the first time, that human CD34+CD38- early HSCs are subject to preferential depletion and functional impairment in vivo in the BM of humanized mice with chronic HIV-1 infection, in a pDC-dependent fashion." (PMID 28759657, 2017).
HIV-1 infection (continued). "Chronic HIV-1 infection preferentially depleted CD34+CD38- early HPCs in the BM and reduced their proliferation potential in vivo in both HIV-1-infected patients and humanized mice, while CD34+CD38+ intermediate HSCs were relatively unaffected." (PMID 28759657, 2017). "Compared to HCs, both IRs and INRs showed a significant increased level of CD38+HLA-DR+CD8+ T cells during chronic HIV-1 infection (p < 0.0001)." (PMID 28018346, 2016). "Our data show for the first time a positive association between ex vivo T cell activation (CD38 expression) and both plasma IFN-I activity and IFNα levels in HIV-1 infection." (PMID 23437155, 2013). "We found that CD38 alone was lower in the adolescents with longer duration of HIV-1 infection despite both age groups having similar matched HIV-1 viral load." (PMID 23029209, 2012). "During HIV-1 infection immune hyperactivation is accompanied by up-regulation of surface expression of CD38 and HLA-DR on CD4 and CD8 T cells." (PMID 16181494, 2005). "Enhanced early activation and coexpression of CD38 and HLA-DR in TIGIT+NK cells were detected compared to TIGIT−NK cells, both of which were inversely associated with the decrease in CD4 T-cell counts in both acute and chronic HIV-1 infection." (PMID 33717085, 2021). "HLA-DR and CD38 are activation markers on T cells during HIV-1 infection." (PMID 33968041, 2021). "In addition, the cell counts of CD34+CD38+ intermediate HPCs showed only minor recovery by the depletion of pDCs during chronic HIV-1 infection, which is consistent with the slight decrease in proportion of CD34+CD38+ intermediate HPCs." (PMID 28759657, 2017). "Notably, the depletion of pDCs significantly changed the percentage of CD34+CD38- early HPCs in the BM from humanized mice with chronic HIV-1 infection." (PMID 28759657, 2017). "Consistent with the preferential reduction of CD34+CD38- HPCs, BrdU-positive CD34+CD38- early HPCs were significantly decreased by chronic HIV-1 infection; meanwhile, the proliferation of CD34+CD38+ intermediate HPCs was only mildly reduced by chronic HIV-1 infection." (PMID 28759657, 2017). "Increased expression of CD38 and HLA-DR on CD4+ and CD8+ T cells in untreated HIV-1 infection has been associated with rapid disease progression and that degree of immune reconstitution following combination antiretroviral therapy is inversely associated with immunological activation." (PMID 26925299, 2015). "Since expression of activation markers CD38 and HLA-DR on circulating T cells is a validated predictor of disease progression in chronic HIV-1 infection, we asked if interferon exposure would increase expression of one or both of these markers in vivo as it does in vitro." (PMID 22291932, 2012). "Thus, augmented CD38 expression induced by calcitriol might have a role in reducing HIV-1 infection of CD4+ T cells." (PMID 31550271, 2019). "However, syphilis infection regulates γδ T-cell activation status following the different stage of HIV-1 infection, that is, the frequencies of CD38+, HLA-DR+, and CD38+HLA-DR+ γδ T cells were decreased in patients with AHI but they were increased in patients with CHI." (PMID 28871259, 2017). "Thus, we hypothesized that pDCs may be responsible for the depletion of CD34+CD38- early HPCs and their functional impairment during chronic HIV-1 infection." (PMID 28759657, 2017). "We found an upregulation of pro-inflammatory markers, i.e., HLA-DR, CD38, CD86, and CD80, during early HIV-1 infection stage in several organs, which persisted into the late infection stages." (PMID 39575258, 2024). "CSF monocytes also exhibited marked activation during acute HIV-1 infection, with elevated surface expression of both CD169 and CD38." (PMID 34874976, 2021). "This was despite the fact that the relative increase in CD38+ CD4+ T cells was comparable between the vaccinia and primary HIV-1 infection cohorts, as previously reported." (PMID 33477692, 2021).
HIV-1 infection (continued). "Our results demonstrated that platelet-CD4+ T cell aggregates expressed higher CD38/HLA-DR and PD-1 levels than their counterparts in all groups, suggesting the potential permissiveness of platelet-CD4+ T cell aggregates to HIV-1 infection." (PMID 34987521, 2021). "The expression of CD38 and HLA-DR on CD8+ T cells has been broadly used to evaluate immune activation in HIV-1 infection." (PMID 30050532, 2018). "In sharp contrast to the activation profile typically observed in HIV-1 infection, the three PEC subjects presenting the highest expression of HLA-DR in CD8+ T cells also showed very low expression of CD38." (PMID 30050532, 2018). "We discovered that HIV-1 infection depleted CD34+CD38- early HPCs and functionally impaired human CD34+ HPCs in the BM of patients and humanized mice with HIV-1 infection." (PMID 28759657, 2017). "To define PB kinetics in HIV-1 infection, we assessed the frequencies of CD3−CD19+CD27+CD38+++ cells before and upon HIV-1 infection." (PMID 28943879, 2017). "In this respect it is interesting that Hurst showed that the expression of HLA-DR and CD38 on CD4+ and CD8+ T cells correlated with the size of total HIV-1 DNA at primary HIV-1 infection." (PMID 29375579, 2017). "Further analysis indicated that the frequency of CD34+CD38- early HPCs was largely decreased in humanized mice with chronic HIV-1 infection, while the proportion of intermediate CD34+CD38+ HSCs was relatively expanded." (PMID 28759657, 2017). "HIV-1 p24+ CD8 negative Tem, that included DN and CD4 T cells, were characterized by higher expression of HLADR/CD38, Ki67, and CCR5, all of which are markers of successful HIV-1 infection of CD4 T cells." (PMID 27870882, 2016). "Recent studies of HIV-1 infection in BLT mice and patients have found evidence of elevated CD38+HLA-DR+ CD8+ T cells in blood." (PMID 22640559, 2012). "Here, we used polychromatic flow cytometry to examine the co-expression of CD38, CD27 and CD28 on total T cells and antigen-specific (HIV, CMV) T cells in a cohort of adults in early HIV-1 infection (within 6 months of acquisition)." (PMID 19198651, 2009). "In contrast, pDC depletion did not influence the percentages of CD34+CD38- early HPCs (CD38 expression) and their proliferation in vivo indicated by BrdU expression in the BM in the absence of HIV-1 infection." (PMID 28759657, 2017). "Total CMV IgG was associated with higher CD4 T cell activation (HLA-DR+CD38+), and terminally differentiated (CD57+ and CD27−CD28−) CD4 and CD8 T cells in CMV-positive individuals irrespective of HIV-1 infection." (PMID 28806406, 2017). "For this reason, we assessed the effect of IFNα administration on CD38 expression in HCV-infected subjects, who do not manifest the elevated CD38 levels that are seen in HIV-1 infection." (PMID 23437155, 2013). "As with the data regarding HIV-1 infection and CD4 T cell depletion we first compared activation of T cells by their expression of CD25, CD38, and HLA-DR in donor-matched tissues infected with a T/F HIV-1 construct, NL-1051.TD12.ecto and a control C/R HIV-1 variant, NL-SF162.ecto." (PMID 23236398, 2012). "From our results, we did not see an increase in susceptibility to HIV-1 infection in the CD28+, CD38+ or HLA-DR+ CD8+ T-cell subsets." (PMID 18923697, 2008). "However, we also found increased CD38/HLA-DR coexpression on the surface of NK cells, including TIGIT+NK and TIGIT−NK cells, in the first, third and twelfth month of HIV-1 infection and in chronic infection over 2 years compared to healthy controls (all P < 0.0001)." (PMID 33717085, 2021). "Summarized data further demonstrated that chronic HIV-1 infection significantly reduced CD34+CD38- early HPCs by nearly 8-fold as compared to the non-infected animals; meanwhile, the proportion of CD34+CD38+ intermediate HPCs was increased from 76% to nearly 100% as shown in the stacked bar graph." (PMID 28759657, 2017).
HIV-1 infection (continued). "Although a previous study suggested that HIV-1 has the potential to infect intermediate CD34+CD38+ HPCs, we found that p24 expression was absent in BM CD34+ HPCs from humanized mice with HIV-1 infection; in contrast, CD3+ T cells showed high levels of p24 expression (10.5%)." (PMID 28759657, 2017).